TNFRSF9 (TNF receptor superfamily member 9)
Description:
Receptor for TNFSF9/4-1BBL. Conveys a signal that enhances CD8(+) T-cell survival, cytotoxicity, and mitochondrial activity, thereby promoting immunity against viruses and tumors (Probable).
Synonyms: CD137; ILA; 4-1BB; CDw137; IMD109
Tractability: Small molecule: a structure with a bound ligand is known. Antibody: a drug acting on it is in phase 2 or 3 trials; its Gene Ontology location is reachable by antibodies, with high confidence; UniProt places it where antibodies can reach, with medium confidence; UniProt predicts a signal peptide or a membrane-spanning region; the Human Protein Atlas places it where antibodies can reach. PROTAC: ubiquitination databases record sites on it.
Target class: Membrane receptor
Gene: Protein-coding gene on chromosome 1 (7,915,871 to 7,943,165, reverse strand). Ensembl gene ENSG00000049249.
Subcellular location: Cell membrane
Subcellular location (Human Protein Atlas): Plasma membrane; Nucleoli
Pathways (Reactome):
Immune System: TNFs bind their physiological receptors
Gene Ontology:
Molecular function: protein binding; signaling receptor activity
Biological process: apoptotic process; negative regulation of cell population proliferation; regulation of cell population proliferation
Cellular component: plasma membrane; external side of plasma membrane
Genetic constraint (gnomAD): Loss-of-function variants: 11 observed, 20.43 expected, observed/expected ratio (o/e) 0.54, 90% interval 0.34 to 0.89. The upper end of that interval is the gene's LOEUF score, 0.89, which puts it in group 3 of 6, group 1 being the genes least tolerant of losing a copy. Missense variants: 265 observed, 281.86 expected, observed/expected ratio (o/e) 0.94, 90% interval 0.85 to 1.04. Synonymous variants: 123 observed, 109.56 expected, observed/expected ratio (o/e) 1.12, 90% interval 0.97 to 1.3.
Gene-disease validity (ClinGen):
ClinGen rates the evidence that TNFRSF9 causes each of these diseases.
immunodeficiency 109 with lymphoproliferation (autosomal recessive): Definitive.
Homologues: Orthologues: chimpanzee TNFRSF9 (99% identical), macaque TNFRSF9 (95% identical), dog TNFRSF9 (78% identical), pig TNFRSF9 (70% identical), rabbit TNFRSF9 (69% identical), rat Tnfrsf9 (59% identical), mouse Tnfrsf9 (58% identical), guinea pig TNFRSF9 (55% identical), tropical clawed frog tnfrsf9 (33% identical). Paralogues in human: TNFRSF21 (26% identical), CD27 (25% identical), LTBR (22% identical), TNFRSF11A (21% identical), CD40 (20% identical), RELT (20% identical), TNFRSF11B (20% identical), TNFRSF1B (20% identical), NGFR (19% identical), TNFRSF4 (19% identical), TNFRSF25 (18% identical), TNFRSF1A (18% identical), and 9 more.
Diseases named in the same sentence as TNFRSF9 in open-access papers:
TNFRSF9 is named in the same sentence as 237 diseases in open-access papers, as found by Europe PMC text mining. Sharing a sentence is not in itself a finding about the gene and the disease. The quoted sentences say what the papers report.
melanoma (90 papers, 2009 to 2025). A malignant, usually aggressive tumor composed of atypical, neoplastic melanocytes. "In addition, TNFRSF9 methylation has been reported to serve as a biomarker in the context of immunotherapies in melanoma." (PMID 33932142, 2021). "Furthermore, the presence of TNFRSF9+ Tregs correlates with the composition of tumor-infiltrating lymphocytes and their ability to recognize antigens, marking them as valuable biomarkers for predicting responses to immune checkpoint inhibitors in melanoma patients." (PMID 40570022, 2025). "Conversely, the CM T-cell data obtained from a previously published melanoma single-cell dataset that we downloaded, the expression of PDCD1 and CTLA-4 was higher than that of TNFRSF9." (PMID 35894206, 2022). "Treg signature genes CXCR5, TNFRSF9, CCR7, STAT1, GBP4, and EOMES were significantly upregulated in the young cohort and were correlated with higher survival in melanoma, while ID3, IL-17A, IL-17F, RDH10 and IL-11 were significantly upregulated in the old cohort." (PMID 36135194, 2022). "The overall survival rate of patients with high expressions of CCR7, CXCR5, EOMES, GBP4, TNFRSF9 and STAT1 in melanoma was significantly higher, which is consistent with the significantly higher survival rate observed for the young cohort receiving immunotherapy." (PMID 36135194, 2022). "Recently, we could identify DNA methylation of the immune checkpoint tumor necrosis factor receptor super family member 9 (4-1BB, TNFRSF9) as a predictive biomarker for response to immunotherapy in melanoma patients." (PMID 32861198, 2020). "We conducted similar analysis for two independent cohorts of melanoma patients with anti-PD-1 treatment, but could not observe significant correlation between TI-Treg-specific expression level of TNFRSF9 with the anti-PD-1 response rate." (PMID 33598101, 2021).
breast cancer (40 papers, 2013 to 2026). A primary or metastatic malignant neoplasm involving the breast. "Our findings suggest that elevated levels of TNFRSF9 protein increase the risk of breast cancer, supported by secondary evidence strength." (PMID 39351539, 2024). "Our research enhances the genetic evidence linking TNFRSF9 elevation to an increased risk of breast cancer." (PMID 39351539, 2024). "Expression of TNFRSF9 in breast cancer is significantly decreased compared to adjacent normal counterpart, and the reduction increases in the breast cancer cells with metastatic and malignant features." (PMID 40506992, 2025). "Studies have reported that TNFRSF9 suppresses tumor progression in breast cancer and that TNFSF9 reverse signaling induces apoptosis in non-small cell lung cancer cells, suggesting a potential role in the antitumor activity of DiPRO1." (PMID 39009887, 2024). "Decreased levels of CASP8, DDX58, CPNE1, ULK3, PARK7, and BTN2A1, as well as increased levels of TNFRSF9, TNXB, DNPH1, and TLR1, were linked to an elevated risk of breast cancer." (PMID 39351539, 2024). "CASP8, DDX58, CPNE1, ULK3, PARK7, and TNFRSF9 have already been identified as targets in drug development and potential therapeutic targets for breast cancer treatment." (PMID 39351539, 2024). "Our research further corroborates the role of TNFRSF9 in breast cancer and provides new genetic evidence supporting its potential as a therapeutic target." (PMID 39351539, 2024). "We conducted qRT-PCR assays to detect the mRNA expression of TNFRSF9 in breast cancer tissues and paracancerous normal tissues collected from 30 patients." (PMID 35799609, 2022). "In this study, we reveal that, through upregulating TNFRSF9 in breast cancer, the PAX6 expression can be downregulated through inhibiting p38 phosphorylation and preventing tumor growth." (PMID 35799609, 2022). "We also propose an agonistic TNFRSF9 antibody as a potential antibody for breast cancer immunotherapy." (PMID 35799609, 2022). "The western blot assay result indicates the TNFRSF9 protein expression's downregulation in eight matched breast cancer tissues and normal tissues." (PMID 35799609, 2022). "The expression of TNFRSF9 in breast cancer is significantly decreased and related to metastasis and malignant." (PMID 35799609, 2022). "To further investigate the role of TNFRSF9 in breast cancer, we knocked down TNFRSF9 through transfecting MCF-7 cells and ZR-75-30 with si-TNFRSF9, as these two cell lines have the lowest TNFRSF9 expression in all the breast cancer cell lines." (PMID 35799609, 2022). "In both breast cancer tissues and cell lines, the levels of TNFRSF9 are significantly decreased, and breast cancer cell development will be promoted with knockdown of TNFRSF9." (PMID 35799609, 2022). "In this study, we report that TNFRSF9 regulates the cell proliferation, invasion, and apoptosis of breast cancer cells through regulating the phosphorylation of p38, thus further regulating the expression of PAX6." (PMID 35799609, 2022). "In breast cancer, TNFSF9 is cross-linked with TNFRSF9, which promotes monocyte/macrophage migration to the tumor microenvironment and osteoclast generation by upregulation of FRA1 expression, thereby promoting breast cancer metastasis." (PMID 34517345, 2021). "In our study, we reveal a possible inhibitory immune checkpoint molecule TNFRSF9 for breast cancer treatment where the agonistic antibody of TNFRSF9 may be effective for breast cancer immunotherapy." (PMID 35799609, 2022). "It is highly likely that a similar axis exists in breast cancer cells between TNFRSF9 and p38 or p38 and PAX6, which could be further investigated in the future." (PMID 35799609, 2022). "As a result, the agonistic TNFRSF9 antibody may be a novel molecule for breast cancer therapies." (PMID 35799609, 2022).
breast cancer (continued). "Gene expression analyses further reveal elevated levels of classic brown (MYF5, EVA1, OPLAH) and beige (CD137/TNFRSF9, TBX1) adipocyte markers, along with PRDM16-a key regulator of brown adipocyte differentiation-in breast cancer xenografts." (PMID 41498391, 2026). "High gene expression of TNFRSF9, HOMER1, and LRP1 were all significantly correlated with worse relapse free survival in breast cancer." (PMID 39483900, 2024). "In summary, this study proposed a novel TNFRSF9/p38/PAX6 axis that contributes to tumor suppression, which suggests a potential immunotherapy target for breast cancer." (PMID 35799609, 2022). "Therefore, agonistic TNFRSF9 antibody may be a novel therapy for breast cancer patients." (PMID 35799609, 2022). "Consistent with this hypothesis, MDA-MB-231 and MCF7 breast cancer cells with high levels of GalCer showed lower activity of the TNFRSF1B and TNFRSF9 promoters than cells lacking GalCer." (PMID 38254878, 2024).
lymphoma (37 papers, 2012 to 2026). A malignant (clonal) proliferation of B- lymphocytes or T- lymphocytes which involves the lymph nodes, bone marrow and/or extranodal sites. "The observed defects in AKT and NF-κB signaling provide mechanistic insights into TNFRSF9 deficiency, implicating these pathways in immune dysregulation, impaired antiviral responses, and increased lymphoma susceptibility." (PMID 40843003, 2025). "Another gene upregulated in P3HR1 lymphomas is TNFRSF9 (4-1BB; CD137)." (PMID 32542010, 2020). "Variants in TNFRSF9 cause immunodeficiency 109 with lymphoproliferation (IMD109, OMIM #620282), a rare autosomal recessive disorder characterized by immunodeficiency, recurrent infection, hypogammaglobulinemia, EBV viremia, and EBV-induced lymphoproliferative disorders or lymphoma." (PMID 40843003, 2025).
COVID-19 (31 papers, 2021 to 2025). A disease caused by infection with severe acute respiratory syndrome coronavirus 2. "COVID-19 can induce cytokine storms, such as IL6, IL32, CD83, CCL2, CXCL11, the TNF family (TNFSF9 and the receptor TNFRSF9), and integrin-related genes, which exacerbates COVID-19 related myocarditis and decreases the prognosis of patients requiring ECMO treatment." (PMID 39026189, 2024). "Compared with the control data, LAMA4 and VEGFC were highly expressed in children with myocarditis and COVID-19, whereas APOE and TNFRSF9 were expressed at low levels." (PMID 39026189, 2024).
ovarian carcinoma (27 papers, 2009 to 2025). A malignant neoplasm originating from the surface ovarian epithelium. "In tubo‐ovarian cancer, activated Treg cells (TNFRSF9+) tended to accumulate as tumour progressed from early to late stage, illustrating an immunosuppressive property." (PMID 41275425, 2025). "Differential gene expression analysis indicated that both CD8 Trm cells and TNFRSF9 Treg cells contribute to immune responses in early‐stage tubo‐ovarian cancer." (PMID 41275425, 2025).
autoimmune disease (23 papers, 2012 to 2026). A disorder resulting from loss of function or tissue destruction of an organ or multiple organs, arising from humoral or cellular immune responses of the individual to their own tissue constituents. "TNFRSF9 is a promising target for immunotherapy in both autoimmune diseases and malignancies." (PMID 40843003, 2025). "TNFRSF9 may play a role in autoimmune diseases and immune response to infections, and may be a target molecule for cancer therapy." (PMID 38401037, 2024). "Increased levels of soluble TNFRSF9 have been reported in sera from patients with autoimmune diseases, suggesting that it may act as a natural regulator of immune responses." (PMID 36756308, 2023). "Currently, the prevailing theory is that TNFRSF9 agonists can be used to treat cancers and autoimmune diseases mainly mediated by CD4+ T cells, but may worsen autoimmune diseases mediated by CD8+ T cells." (PMID 35894206, 2022).
lung carcinoma (22 papers, 2014 to 2026). "Results from our study together with these previous reports confirm that TNFRSF9 is associated with the activation of TI-Tregs, and their inhibition may boost anticancer treatments including lung cancer immunotherapy by reducing immune suppressive function of Tregs in tumor." (PMID 33598101, 2021). "Therefore, we conclude that the expression level of TNFRSF9 in TI-Tregs is a novel biomarker that can predict the prognosis of anticancer treatment and response to anti-PD-1 immunotherapy in human lung cancer." (PMID 33598101, 2021). "In addition, we tested whether the expression level of TNFRSF9 in TI-Tregs correlates with stage of lung cancer and found that it was significantly higher in stage-4 patients compared with stage-1 patients (P = 0.03, Mann-Whitney U test)." (PMID 33598101, 2021).
atherosclerosis (21 papers, 2013 to 2025). A disease characterized by the build-up of fatty material and calcium deposition in the arterial wall resulting in partial or complete occlusion of the arterial lumen. "TNF receptor superfamily member 9 (TNFRSF9), also known as CD137, is implicated in inflammatory diseases such as atherosclerosis and Crohn’s disease." (PMID 33674626, 2021). "In the pathological process of atherosclerosis, the activation of TNFRSF9 is strongly correlated with the exacerbation of plaque formation and the vascular calcification process." (PMID 40599317, 2025). "miR-654-3p was found to reduce inflammation by targeting ADAM10 and RAB22A (both promoters of atherosclerosis) and TNFRSF9 (TNF receptor family member 9)." (PMID 39201485, 2024). "Therefore, TNFRSF9 is considered a potential biomarker of atherosclerosis." (PMID 40599317, 2025). "Activation of TNFRSF9 signaling on the macrophage surface modulates the STAT6/PPARδ signaling pathway, which induces the polarization of macrophages in atherosclerosis toward the M2 type." (PMID 40599317, 2025). "Second, populations with other cardiovascular diseases, such as myocardial infarction, coronary artery disease, atherosclerosis, and stroke, were not included, which could help further determine the specificity of elevated TNFRSF9 in AAA." (PMID 40599317, 2025).
colon carcinoma (19 papers, 2010 to 2024). "For C4 (Th17), only nine DEGs, including TNFRSF9 and CXCL13 were screened between colon cancer and rectal cancer." (PMID 33584715, 2020).
leukemia (19 papers, 2009 to 2025). A malignant (clonal) hematologic disorder, involving hematopoietic stem cells and characterized by the presence of primitive or atypical myeloid or lymphoid cells in the bone marrow and the blood. "TNFRSF9 is targeted by Urelumab, currently under investigation for its efficacy against leukemia, multiple myeloma, malignant tumors, solid tumors, and B-cell non-Hodgkin’s lymphoma." (PMID 39351539, 2024). "CD8 linker joined to CD8TM, CD4TM, TNFRSF19, TNFRSF16, and TNFRSF9 were then tested for surface expression and killing of CD19+ leukemia cell lines." (PMID 34893603, 2021).
pancreatic cancer (17 papers, 2013 to 2025). "Associations between some proteins [e.g. matrix metalloproteinase-7 (MMP7), hepatocyte growth factor (HGF) and tumour necrosis factor receptor superfamily member 9 [TNFRSF9)] and risk of pancreatic cancer were time-varying, with higher levels associated with higher short-term risk." (PMID 35064782, 2022). "In recent years, many studies have found that TNFRSF9/TNFSF9 is involved in immune regulation of various tumors, including pancreatic cancer and hepatocellular carcinoma, but their specific role in tumor development has not been clarified." (PMID 35894206, 2022).
glioma (14 papers, 2014 to 2025). A benign or malignant brain and spinal cord tumor that arises from glial cells (astrocytes, oligodendrocytes, ependymal cells). "Using WGCNA and LASSO algorithms, we identified four MHC-related genes (TNFSF14, MXRA5, FCGR2B, and TNFRSF9) as prognostic biomarkers for glioma." (PMID 40429753, 2025). "To further explore the role of MHC in gliomas, we used LASSO regression analysis and identified four genes (TNFSF14, MXRA5, FCGR2B, and TNFRSF9) related to the major histocompatibility complex (MHC)." (PMID 40429753, 2025). "Infected glioma cells express elevated levels of 4-1BB ligand, which binds to TNFRSF9 (CD137; 4-1BB), a co-stimulatory receptor." (PMID 38022620, 2023).
Obesity (13 papers, 2012 to 2025). Accumulation of substantial excess body fat. "Studies have also indicated that the removal of TNFRSF9 reduced obesity-induced adipose inflammation and improved both insulin resistance and glucose tolerance." (PMID 30250206, 2018). "In this study, we investigated whether 4-1BB, a member of the TNF receptor superfamily (TNFRSF9) that provides inflammatory signals, participates in obesity-induced skeletal muscle inflammation." (PMID 24453430, 2013). "Conversely, the other TNFRSF gene members (e.g., TNFRSF4, TNFRSF9, TNFRSF14) were observed to be positively correlated with obesity in mammalian species." (PMID 35053107, 2022). "Subsequently, we examined the effect of quercetin on inflammatory receptors such as TNF receptor superfamily member 9 (4-1BB) and toll-like receptor 4 (TLR4), which are known to promote obesity-induced inflammatory responses in skeletal muscle." (PMID 25614714, 2014).
gastric cancer (11 papers, 2015 to 2025). A primary or metastatic malignant neoplasm involving the stomach. "Meanwhile, the immune status of tumors are related to the TNFRSF9 expression levels in gastric cancer." (PMID 40072746, 2025).
colorectal cancer (10 papers, 2019 to 2025). A primary or metastatic malignant neoplasm that affects the colon or rectum. "TNFRSF9 is associated with various tumors, and somatic variants have been identified in hematopoietic, lymphoid, lung, and colorectal cancers." (PMID 40843003, 2025).
psoriasis (9 papers, 2014 to 2025). An autoimmune condition characterized by red, well-delineated plaques with silvery scales that are usually on the extensor surfaces and scalp. "Recent genome-wide association studies (GWAS) have identified SNPs nearHLA-C,TNFRSF9, andLCE3A as more strongly associated with psoriasis than PsA, whereas SNPs nearIL-23R andTNFAIP3 were more strongly associated with PsA than PsC31." (PMID 31583079, 2019). "Three of the identified psoriasis risk variants had a stronger association with PsC than PsA (rs12189871 near HLA-C, rs4908742 near TNFRSF9, rs10888503 near LCE3A), whereas two had a stronger association with PsA than PsC (rs12044149 near IL23R, rs9321623 near TNFAIP3)." (PMID 36826011, 2023). "Loss of TNFRSF9 expression due to psoriasis susceptibility alleles may thus have either pro- or anti-inflammatory effects by altering the balance of forces affecting neutrophil apoptosis." (PMID 24885462, 2014). "We identified SNPs near TNFRSF9 at which psoriasis susceptibility variants disrupted binding sites for AP-1 (rs6687168) and NF-κB (rs6661746), where both binding sites were also enriched with respect to sequences adjacent to genes co-expressed with TNFRSF9 in neutrophils." (PMID 24885462, 2014). "Moreover, in agreement with microarray data, RT-PCR confirmed significant elevation of TNFRSF9 expression in psoriasis lesions as compared to uninvolved and normal skin." (PMID 24885462, 2014).